EPHA7 (EPH receptor A7)
Description:
Receptor tyrosine kinase which binds promiscuously GPI-anchored ephrin-A family ligands residing on adjacent cells, leading to contact-dependent bidirectional signaling into neighboring cells. The signaling pathway downstream of the receptor is referred to as forward signaling while the signaling pathway downstream of the ephrin ligand is referred to as reverse signaling. Among GPI-anchored ephrin-A ligands, EFNA5 is a cognate/functional ligand for EPHA7 and their interaction regulates brain development modulating cell-cell adhesion and repulsion. Has a repellent activity on axons and is for instance involved in the guidance of corticothalamic axons and in the proper topographic mapping of retinal axons to the colliculus. May also regulate brain development through a caspase(CASP3)-dependent proapoptotic activity. Forward signaling may result in activation of components of the ERK signaling pathway including MAP2K1, MAP2K2, MAPK1 and MAPK3 which are phosphorylated upon activation of EPHA7.
Synonyms: EHK-3; EK11; hEK11; EHK3
Tractability: Small molecule: an approved drug acts on it; a structure with a bound ligand is known; a high-quality ligand is known; it has a high-quality binding pocket; it belongs to a druggable protein family. Antibody: UniProt places it where antibodies can reach, with high confidence; its Gene Ontology location is reachable by antibodies, with high confidence; UniProt predicts a signal peptide or a membrane-spanning region. PROTAC: ubiquitination databases record sites on it; its protein half-life has been measured; a small molecule that binds it is known.
Target class: Tyrosine protein kinase Eph family; Protein Kinase; TK protein kinase group; Kinase; Enzyme
Safety:
Unwanted effects reported when the protein is acted on. In parentheses: how it was acted on, where the effect was seen, and who reports it.
bleeding (source: ClinPGx)
Gene: Protein-coding gene on chromosome 6 (93,240,020 to 93,419,687, reverse strand). Ensembl gene ENSG00000135333.
Subcellular location: Cell membrane
Subcellular location (Human Protein Atlas): Principal piece
Pathways (Reactome):
Developmental Biology: EPH-Ephrin signaling; EPH-ephrin mediated repulsion of cells; EPHA-mediated growth cone collapse
Gene Ontology:
Molecular function: protein binding; axon guidance receptor activity; chemorepellent activity; GPI-linked ephrin receptor activity; protein tyrosine kinase activity; transmembrane-ephrin receptor activity; ATP binding; ephrin receptor activity; ephrin receptor binding; growth factor binding; protein kinase activity; transmembrane receptor protein tyrosine kinase activity
Biological process: ephrin receptor signaling pathway; regulation of ERK1 and ERK2 cascade; regulation of peptidyl-tyrosine phosphorylation; axon guidance; brain development; branching morphogenesis of a nerve; negative chemotaxis; phosphorylation; positive regulation of neuron apoptotic process; regulation of cell-cell adhesion; regulation of protein autophosphorylation; cell surface receptor protein tyrosine kinase signaling pathway; modulation of chemical synaptic transmission; negative regulation of collateral sprouting; negative regulation of phosphatidylinositol 3-kinase/protein kinase B signal transduction; negative regulation of synapse assembly; positive regulation of apoptotic process; regulation of postsynapse organization
Cellular component: plasma membrane; dendrite; glutamatergic synapse; hippocampal mossy fiber to CA3 synapse; membrane; neuromuscular junction; neuronal cell body; postsynaptic density membrane; postsynaptic membrane; postsynaptic specialization membrane; Schaffer collateral - CA1 synapse
Genetic constraint (gnomAD): Loss-of-function variants: 19 observed, 98.79 expected, observed/expected ratio (o/e) 0.19, 90% interval 0.13 to 0.28. The upper end of that interval is the gene's LOEUF score, 0.28, which puts it in group 1 of 6, group 1 being the genes least tolerant of losing a copy. Missense variants: 848 observed, 1,123.9 expected, observed/expected ratio (o/e) 0.75, 90% interval 0.71 to 0.8. Synonymous variants: 393 observed, 381.21 expected, observed/expected ratio (o/e) 1.03, 90% interval 0.95 to 1.12.
Homologues: Orthologues: chimpanzee EPHA7 (99% identical), macaque EPHA7 (99% identical), rabbit EPHA7 (99% identical), pig EPHA7 (99% identical), dog EPHA7 (99% identical), rat Epha7 (99% identical), mouse Epha7 (98% identical), guinea pig EPHA7 (95% identical), tropical clawed frog epha7 (92% identical). Paralogues in human: EPHA5 (63% identical), EPHA4 (62% identical), EPHA3 (62% identical), EPHA6 (59% identical), EPHB2 (57% identical), EPHA8 (56% identical), EPHB1 (56% identical), EPHB3 (54% identical), EPHA10 (51% identical), EPHA2 (50% identical), EPHB4 (48% identical), EPHA1 (42% identical), and 41 more.
Diseases named in the same sentence as EPHA7 in open-access papers:
EPHA7 is named in the same sentence as 86 diseases in open-access papers, as found by Europe PMC text mining. Sharing a sentence is not in itself a finding about the gene and the disease. The quoted sentences say what the papers report.
colorectal cancer (16 papers, 2008 to 2022). A primary or metastatic malignant neoplasm that affects the colon or rectum. "EphA7 is downregulated in colorectal cancer, prostate cancer, and gastric cancer by hypermethylation of its promoter." (PMID 35103233, 2022). "In previous works, we found that downregulation of EphA7 in colorectal cancer and gastric cancer by hypermethylation." (PMID 35103233, 2022). "It has been shown that EphA7 expression is lost in colorectal cancer, also as a result of epigenetic silencing mediated by CpG methylation of the promoter." (PMID 33430066, 2021). "Colorectal cancer with EPHA7-MUT had the worst prognosis in TCGA cohort (HR = 5.21 [95% CI, 2.22–12.21], adjusted P < 0.0001)." (PMID 33526018, 2021). "Here, in this study we compared the levels of CCR5, CCL5, PDGF, and EphA7 in patients with colorectal carcinoma and healthy controls in order to assess these parameters in terms of early diagnosis." (PMID 31505877, 2019). "The expression of EPHA7 is downregulated in colorectal cancer and upregulated in prostate and lung cancer." (PMID 28611294, 2017). "On the other hand, also downregulation of Eph receptors can lead to increased metastasis and carcinogenesis as shown for EphA1 in colorectal cancer, EphA7 in prostate carcinomas, and EphB6 in melanoma." (PMID 20224755, 2010). "For instance, mutations have been identified in EphA3 in melanoma and glioblastoma, and EphA3, EphA4, EphA7, and EphB6 in colorectal cancers." (PMID 20224755, 2010). "EphA7 expression is frequently silenced in human colorectal carcinoma by aberrant promoter methylation." (PMID 18366728, 2008). "However, reduced expression of EphA7 due to hypermethylation of CpG island was found in prostate cancer, gastric cancer, and colorectal cancer." (PMID 35103233, 2022). "Indeed, EphA7 has been shown to play both tumor-suppressive and oncogenic roles in colorectal cancer, prostate cancer, and lung cancer." (PMID 35103233, 2022). "352A > G) in EPHA7 was reported in a colorectal cancer cell line." (PMID 34399808, 2021). "This could partially explain why EPHA7-MUT colorectal cancer was the only one that presented with worse OS in the validation cohort, because the harmful prognostic impact of EPHA7-MUT outweighed its ICI treatment benefits in colorectal cancer." (PMID 33526018, 2021). "Interestingly, colorectal cancer patients achieved longer survival with EPHA7-WT instead of EPHA7-MUT (HR = 4.37 [95% CI 0.81–23.46], adjusted P = 0.08)." (PMID 33526018, 2021). "Decreased EphA7 expression occurs in colorectal cancers, but it has not been associated with any clinical parameters." (PMID 33007931, 2020). "This is the first study that has investigated whether the cytokines/chemokines CCL5, CCR5, PDGF, and EphA7 have significant value for early diagnosis of colorectal carcinomas." (PMID 31505877, 2019). "In subgroup analysis, the survival advantage of EPHA7-MUT vs EPHA7-WT was prominent and consistent across sex, age, drug class, cancer type (except for colorectal cancer), TMB level, and CNA level (all Pinteraction > 0.05)." (PMID 33526018, 2021). "PDGF-BB, EphA7, CCR5, and CCL5 levels of the patients with colorectal carcinoma were significantly higher compared to the control group (p < 0.001 for each comparison)." (PMID 31505877, 2019). "We were able to validate previous findings describing frequent hypermethylation events of EPHA7, MGMT and MLH1 in colorectal cancer patients, RARB in prostate tumors, and CASP8 in glioblastoma." (PMID 28581523, 2017). "It is important that the effects of each receptor are investigated in a cancer-specific manner as it is evident that Eph receptors do not always function the same way; EphA7, e.g., has a tumour-suppressive role in colorectal cancer and prostate cancer, but is tumour-promoting in NSCLC." (PMID 33430066, 2021). "Moreover, reduced to absent EPHA7 expression has also been found in human colorectal cancer." (PMID 27533460, 2016).
breast cancer (14 papers, 2010 to 2024). A primary or metastatic malignant neoplasm involving the breast. "Overexpression of EPHA4 and EPHA7 has been associated with worse prognosis in breast cancer as well as glioma." (PMID 35204461, 2022). "An increased expression of EphA4, EphA7 and EphA10 receptors was also found in breast cancer, which is associated with poor prognosis, and EphA4 is reported to promote breast cancer cell proliferation, migration, and invasion via the transforming growth factor-beta (TGFβ) signalling pathway." (PMID 36830852, 2023). "Given the important roles of FOXM1, EPHA4 and EPHA7 on breast cancer outcome, FOXM1 and miR-135a were good candidates for a siRNA knockdown study." (PMID 27528030, 2016). "In breast cancer, elevated RNA expression of EphA4 had significant prognostic value, as did EphA2, EphA7, and EphB4." (PMID 23738943, 2013). "These analyses confirmed the relevance of EphA2 and EphB4 to human breast cancer progression, and uncovered significant correlations for EphA4, EphA7, and EphB6, which were previously under-investigated in breast cancer." (PMID 21935409, 2011). "Furthermore, Western blot analysis for EPHA2, EPHA4, and EPHA7 was performed in three different human breast cancer cell lines." (PMID 35204461, 2022). "Higher expression level of EPHA7 is correlated with poor prognosis and metastasis in breast cancer." (PMID 34396843, 2021). "We evaluated protein expression of EphA2, EphA4, EphA7, EphB4, and EphB6 in human breast cancer tissue microarrays (TMA) in which we could distinguish expression in tumor epithelium from stromal components, including endothelium." (PMID 21935409, 2011). "In addition, overexpression of NTRK3, EPHA7, and FGFR2 (M subtype-specific TK genes) has been linked to a worse prognosis in breast cancer and could promote TNBC formation." (PMID 36672350, 2023). "Importantly, in MCF-7 breast cancer cells as a model of Luminal A subtype breast cancers, GPR81-regulated genes were significantly associated with multiple GO terms relating to extracellular matrix (ECM) and cell adhesion, including PCDH7, EPHA7, and the Notch ligand DLL4." (PMID 37993804, 2023). "Concerning breast cancer human material in general, some recent studies have attempted to link the expression of EPHA2, EPHA4, and EPHA7 with clinicopathologic parameters and/or survival." (PMID 35204461, 2022). "Among the family members, EPHA2 and EPHB4 are the most studied in breast cancer and additionally EPHA4, EPHA7 and EPHB6 emerged as promising clinical candidates in an expression profile of the individual EPH and ephrin family members." (PMID 26870995, 2016). "In breast cancer, ART increased EPHA8, EPHA10, EFNA2 and reduced EPHA3, EPHA7, and EFNA3." (PMID 38630320, 2024).
prostate carcinoma (11 papers, 2005 to 2022). A carcinoma that arises from epithelial cells of the prostate gland. "In contrast, EphA7 has been assigned a tumour-suppressive role and was found to be downregulated in prostate cancer, the mechanism responsible for this being CpG methylation." (PMID 33430066, 2021). "For example, EPHA7 inhibits malignant growth of prostate cancer by targeting the PI3K/Akt signaling pathway." (PMID 33439936, 2021). "While EphA1 abundance was decreased in prostate cancer cell lines, EphA2, EphA5, EphA6, EphA7, EphA8, and EphA10 levels were elevated in some of the prostate cancer cell lines as compared to the normal prostate cell line." (PMID 29682554, 2018). "The EphA receptors that are decreased or lost in prostate cancer include EphA5 in patients with a Gleason score of 8, EphA6 in LNCaP-19 cell line, and EphA7 in prostate tumor specimens." (PMID 29682554, 2018). "Transcriptional silencing of EphA7 in a subset of prostate cancer cells is regulated by methylation of the EphA7 promoter." (PMID 29682554, 2018). "The presence of EphA7 in primary tumors and its loss in lymph and bone metastases suggests that promoter methylation is perhaps not an early event in prostate cancer." (PMID 29682554, 2018). "The LNCaP gene EPHA7 was expressed in normal prostate and primary prostate cancer only." (PMID 16042785, 2005). "However, EphA7 may also act as a tumor suppressor since EphA7 downregulation is induced by promoter hypermethylation in prostate cancer patients." (PMID 35681118, 2022). "EPHA7 acted as a TSG in modulating cell growth in human colorectal, gastric, and prostate carcinomas." (PMID 27681722, 2016). "Hypermethylation of EPHA7 without a corresponding analysis of gene expression levels has also been reported for human prostate cancer tissues and many human acute lymphoblastic leukemia lines and primary samples." (PMID 27533460, 2016). "In a practical application of multiple expression-platform profiling, our analysis of C4-2 and LNCaP prostate cancer cell lines has identified genes such as CA1, CARD14, and EPHA7 that may be involved in prostate cancer progression." (PMID 16042785, 2005). "Meanwhile, another study proved that ligand-dependent EphA7 but not the truncated secreted form of EphA7 induced prostate cancer cell apoptosis; and tyrosine 791 phosphorylation of EphA7, which is required in prostate cancer cell apoptosis, is dependent on the stimulation of ephrinA5 ligand." (PMID 31685980, 2020). "Among the 20 prostate carcinoma specimens, 13 (65.0%) exhibited undetectable or weak ephrinA5 immunostaining, and 40.0% (8/20) of the tumor tissues had no intense immunostaining of the EphA7 protein." (PMID 29022918, 2017). "Expression analysis of these genes in prostate cancer specimens showed CA1 to be highly expressed in bone metastasis but not expressed in primary tumor and EPHA7 to be expressed in normal prostate and primary tumor but not bone metastasis." (PMID 16042785, 2005).
glioblastoma (9 papers, 2008 to 2022). The most malignant astrocytic tumor (WHO grade IV). "Upregulation of EphA7 in gallbladder adenocarcinoma and glioblastoma has also been shown to be related to metastasis and poor survival." (PMID 35103233, 2022). "A general upregulation of stimulatory immunomodulators was observed in EPHA7-MUT tumors except glioblastoma (GBM), which showed a general downregulation of both inhibitory and stimulatory immunomodulators." (PMID 33526018, 2021). "An increased EphA7 expression is correlated with adverse outcomes in patients with primary and recurrent glioblastoma multiforme." (PMID 31803734, 2019). "In a similar way, EPHA7 has been involved in tumor growth and progression of medulloblastoma and glioblastoma multiforme (GBM) as well as in NSCLC." (PMID 27058903, 2016). "In turn, studies on glioblastoma have shown that patients with tumors expressing EphA7 have shorter survival times compared to the non-expressed group, and the degree of expression inversely correlates with survival." (PMID 33007931, 2020). "These analyses revealed a negative correlation between BMI1 and EPHA7 expression levels for the human follicular lymphoma and medulloblastoma datasets, but not for the glioblastoma datasets (and data not shown)." (PMID 27533460, 2016). "However, other reports showed that EPHA7 has a promoting role in human lung cancers, laryngeal carcinomas, and glioblastoma like an oncogene, but detailed mechanisms are not clear so far." (PMID 27681722, 2016).
lung carcinoma (9 papers, 2008 to 2024). "Of these target genes, the obvious one is EPHA7, which was reported to be up-regulated and, significantly, positively associated with the proliferation of lung cancer cells." (PMID 27681722, 2016). "EphA7 gene mutations were also more frequent in lung cancer specimens." (PMID 39329983, 2024). "EphA7 gene mutations were also found more often in lung cancer specimens." (PMID 39329983, 2024). "PTPRD and EPHA7 mutation are two new biomarkers for predicting the efficacy of immunotherapy independent of TMB or PD-L1 expression in lung cancer." (PMID 36845145, 2023). "In contrast, overexpression of EPHA4 and EPHA7 is correlated with improved outcome in lung cancer." (PMID 35204461, 2022).
gastric cancer (8 papers, 2008 to 2025). A primary or metastatic malignant neoplasm involving the stomach. "The EphA7 expression was found in gastric cell lines and expressed in gastric carcinoma specimens." (PMID 39329983, 2024). "Furthermore, overexpression of EphA7 protein is frequently found in younger patients and in patients with advanced gastric carcinoma." (PMID 18366728, 2008). "The study identified a panel of four mRNAs (AGTR1, DNER, EPHA7, and SUSD5) significantly upregulated in recurrent gastric cancer tissues compared to non‐recurrent tissues." (PMID 39556695, 2024). "A novel liquid biopsy method using a 4‐mRNA biomarker panel (AGTR1, DNER, EPHA7, SUSD5) improves early detection of recurrence in locally advanced gastric cancer." (PMID 39556695, 2024). "While this gene has not been directly linked to Hippo, the related EphA2 receptor was shown to regulate YAP in breast and gastric cancer cells and other EPHA receptors (EPHA4, EPHA5, EPHA7 and EPHA8) emerged as Hippo pathway activators in an siRNA screen in HEK293T cells." (PMID 40869130, 2025).
colon carcinoma (6 papers, 2005 to 2023). "High expression of EPHA4 but reduced expression of EPHB2 is linked with liver metastasis in human colon carcinomas, while high EPHA7 protein expression is associated with worse prognosis in patients with pancreatic cancer." (PMID 35204461, 2022). "The mRNA of EphA7 is strongly upregulated in hepatocellular carcinoma as compared with healthy liver tissue and is downregulated in colon carcinomas." (PMID 18366728, 2008). "The expression of EPHA7 has been observed to be elevated in liver tumors, decreased in colon tumors, and unchanged in lung or kidney tumors." (PMID 16042785, 2005). "For instance, CPNE4 and EPHA7 are already shown to be involved in colon cancer." (PMID 29589558, 2018). "Our logistic regression analysis (the area under the curve was 0.958) supports the notion that PDGF-BB, EphA7, and CCL5 are potential biomarkers for the diagnosis of colon cancer." (PMID 31505877, 2019).